SBK3 (SH3 domain binding kinase family member 3)
Synonyms: SGK110
Tractability: Small molecule: a high-quality ligand is known; it belongs to a druggable protein family. PROTAC: a small molecule that binds it is known.
Target class: Enzyme; Other protein kinase NKF1 family; Kinase; Protein Kinase; Other protein kinase group
Gene: Protein-coding gene on chromosome 19 (55,539,018 to 55,550,284, reverse strand). Ensembl gene ENSG00000231274.
Subcellular location (Human Protein Atlas): Mitochondria
Gene Ontology:
Molecular function: protein binding; protein serine/threonine kinase activity; ATP binding; protein kinase activity; protein serine kinase activity
Genetic constraint (gnomAD): Loss-of-function variants: 16 observed, 11.27 expected, observed/expected ratio (o/e) 1.42, 90% interval 0.95 to 1.9. The upper end of that interval is the gene's LOEUF score, 1.9, which puts it in group 6 of 6, group 1 being the genes least tolerant of losing a copy. Missense variants: 462 observed, 470.27 expected, observed/expected ratio (o/e) 0.98, 90% interval 0.91 to 1.06. Synonymous variants: 217 observed, 211.89 expected, observed/expected ratio (o/e) 1.02, 90% interval 0.92 to 1.15.
Homologues: Orthologues: macaque SBK3 (97% identical), rat Sbk3 (84% identical), mouse Sbk3 (84% identical), chimpanzee SBK3 (64% identical), tropical clawed frog sbk3 (36% identical), Drosophila melanogaster CG4945 (26% identical), Drosophila melanogaster meng (25% identical), Caenorhabditis elegans Y39G8B.5 (18% identical), Caenorhabditis elegans ikke-1 (18% identical). Paralogues in human: SBK1 (32% identical).